RNU1-64P (RNA, U1 small nuclear 64, pseudogene)
Gene: Small nuclear RNA gene on chromosome 6 (11,503,509 to 11,503,671, reverse strand). Ensembl gene ENSG00000202313.
Homologues: Orthologues: chimpanzee U1 (99% identical), macaque U1 (94% identical), guinea pig U1 (71% identical), mouse Gm54446 (61% identical), pig U1 (61% identical), rat U1 (56% identical). Paralogues in human: RNU1-1 (77% identical), RNU1-2 (77% identical), RNU1-21P (77% identical), RNU1-27P (77% identical), RNU1-28P (77% identical), RNU1-3 (77% identical), RNU1-4 (77% identical), RNVU1-18 (77% identical), RNVU1-28 (77% identical), RNVU1-29 (77% identical), RNVU1-31 (77% identical), RNVU1-7 (77% identical), and 134 more.